LINC01482 (long independently transcribed non-coding RNA 1482)
Gene: Long non-coding RNA gene on chromosome 17 (68,591,782 to 68,763,882, forward strand). Ensembl gene ENSG00000267659.
Diseases named in the same sentence as LINC01482 in open-access papers:
LINC01482 is named in the same sentence as 1 disease in open-access papers, as found by Europe PMC text mining. Sharing a sentence is not in itself a finding about the gene and the disease. The quoted sentences say what the papers report.
tumor (1 paper, 2020). "Meanwhile, the other 13 lncRNAs (AC008781.2, HULC, AC100839.1, CRAT37, LINC01198, LINC01482, SMAD1‐AS2, TH2LCRR, DISC1‐IT1, ABCC5‐AS1, NFIA‐AS1, AC007431.1, AC012494.1) were up‐regulated and hypomethylated in CC tumor group which confirmed our previous MethylRad sequencing results." (PMID 32869528, 2020).